CD38 (CD38 molecule)
Diseases named in the same sentence as CD38 in open-access papers (continued):
Sharing a sentence is not in itself a finding about the gene and the disease.
glioma (continued). "Accordingly, we showed that targeting CD38 expression or its activity in the glioma microenvironment inhibited glioma progression and prolonged the lifespan of glioma-bearing mice." (PMID 30159123, 2018). "However, NFE2L1 shapes the tumor immune microenvironment, but its relationship with CD38 needs clarification, indicating potential for glioma therapy." (PMID 40677211, 2025). "This mechanistic insight provides a theoretical foundation for combination therapy, suggesting that the dual blockade of PD‐1 and CD38 may synergistically enhance immune cell function through multiple pathways, thereby improving therapeutic efficacy in glioma." (PMID 40677211, 2025). "The four genes, PARP9, BST1, NMNAT2, and CD38, might be important molecular biomarkers and therapeutic targets for glioma patients." (PMID 36778644, 2023). "CD38 mediated intracellular ATP levels and glioma cell survival." (PMID 36778644, 2023). "We demonstrated an association between increases of glioma CCL5 and CCR5+CD38+HLA-DR+CD8+ TILs." (PMID 31649684, 2019). "Previous studies where glioma cells were injected into CD38-deficient mice revealed that the absence of CD38 in the TME brought about a reduction in tumor size and an improvement in life expectancy." (PMID 31861847, 2019). "Therefore, it seems that CD38 inhibition impedes glioma growth by suppressing the pro-tumoral activity of activated TMMs." (PMID 31861847, 2019). "Microglia in the CNS express CD38, and this expression is increased in glioma." (PMID 31861847, 2019). "Previously we showed that the ectoenzyme CD38 may serve as a useful microenvironmental target to inhibit glioma progression." (PMID 30159123, 2018). "Therefore, CD38 may be a useful molecular biological marker and a prospective therapeutic target for glioma patients." (PMID 39744577, 2025). "Thus, simultaneously targeting both PD‐1 and CD38 may disrupt the multi‐layered immunosuppressive network in the glioma microenvironment, offering a promising strategy for immunotherapy." (PMID 40677211, 2025). "In response to glioma, CCR5+CD38+HLA-DR+CD8+ T cells were activated with a coinciding increase in TEMRA+ (CD45RA+CCR7−)." (PMID 31649684, 2019). "Higher CCL5 protein and mRNA levels were identified in glioma tissues, which was consistent with the immunohistochemistry results revealing both CCL5 and CD38+HLA-DR+CD8+ T cell expression." (PMID 31649684, 2019). "Beyond CLL, the expression rates of CD38 and NGAL-R are high in other tumors such as acute and chronic myeloid leukemias, epithelial carcinomas (esophagus, liver, kidney, endometrial carcinomas) and gliomas." (PMID 37760777, 2023). "According to the results of qRT-PCR, the mRNA expressions of CD38, NADK, PARP9 were significantly elevated in glioma tissues compared with NBT, while the mRNA expressions of NAPRT and PARP6 showed a significant downward trend in glioma tissues." (PMID 36845744, 2023). "Most importantly, it proved that CD38, NMNAT2, PARP9, and BST1 might be important prognostic molecular markers and potential therapeutic targets for glioma patients." (PMID 36778644, 2023). "Being activated in glioma, CCR5+CD38+HLA‐DR+CD8+ T cells express a higher level of PD‐1, suggesting that the PD‐1/PD‐L1 loop may be a potential target for glioma treatment." (PMID 34482648, 2021). "Patients' CCR5+CD38+HLA-DR+CD8+ T cells were further validated and shown to display increases in CD45RA+CCR7− and T-bet+ accompanied by substantial CD107-a, IFN-γ, and Granzyme B levels in response to glioma cells." (PMID 31649684, 2019). "In addition, the CD38+HLA-DR+CD8+ cells expressed higher levels of PD-1, and the presence of CD8+ T cells indicated reinforcement of glioma PD-L1 expression, suggesting that the PD-1/PD-L1 loop may facilitate the maintenance of proper immune responses." (PMID 31649684, 2019).
glioma (continued). "The current study revealed that a subset of effector CD8+ T cells characterized as CD38+HLA-DR+CD8+ existed in both the peripheral blood and the tumor microenvironment, which indicated that the immune system of patients with glioma could recognize the tumor cells at an early stage." (PMID 31649684, 2019).
B-cell lymphoma (20 papers, 2008 to 2026). "CD38 positivity with higher sADO levels was more evident in patients with higher risk stratification in all mature B-cell lymphoma and the B-NHL group." (PMID 39805878, 2025). "Univariate analysis identified male sex, age ≥60 years, myeloid malignancies, B-cell lymphoma, other lymphoid malignancies, bendamustine use, anti-CD20 antibody use, and anti-CD38 antibody use as statistically significant risk factors (P<0.01 for all)." (PMID 41267982, 2025). "We also noted a significant increase in sPD-L1, sPD-1, and sADO levels in CD38-positive mature B-cell lymphoma patients." (PMID 39805878, 2025). "Our study revealed a positive correlation between CD38 expression, sADO, sPD-1, and sPD-L1 in mature B-cell lymphoma patients." (PMID 39805878, 2025). "Higher CD38 expression and extracellular ADO negatively affected HB level and PLT count and positively correlated with the higher risk stratification in mature B-cell lymphoma patients." (PMID 39805878, 2025). "To study the effect of CD38 expression on other laboratory parameters, we found that all CD38-positive mature B-cell lymphoma patients had significant thrombocytopenia compared to CD38-negative patients." (PMID 39805878, 2025). "Nevertheless, little is known about the exact effect of enhanced CD38 expression and extracellular ADO production or their mediated immune-suppressive impact linked to the PD-1/PD-L1 axis in mature B-cell lymphomas." (PMID 39805878, 2025). "Our data revealed a statistically significant positive correlation between CD38 expression % and sPD-L1, sPD-1, and sADO in all mature B-cell lymphoma patients (P-value < 0.01)." (PMID 39805878, 2025). "Our study was conducted on 90 patients, CD38-positive and CD38-negative (measured by flow cytometry), with mature B-cell lymphoma divided into CLL and B-NHL subtypes." (PMID 39805878, 2025). "As a type II transmembrane glycoprotein, the highly expressed CD38 is an important factor in the poor prognosis of B cell lymphoma." (PMID 36823603, 2023). "LMO2 and CD38 expression determined by immunohistochemistry in 75 BL, 12 High-grade B-cell lymphoma, NOS (HGBL,NOS) and 3 Burkitt-like lymphomas with the 11q aberration." (PMID 31484540, 2019). "We reported that T cells with anti-CD38-chimeric antigen receptors (CAR) eliminated B-cell lymphoma cells expressing CD38." (PMID 28090317, 2016). "Adult mice expressing low amounts of RAR-α develop spontaneous T and B cell lymphomas and had very low amounts of the RA-inducible gene, CD38, in thymus and bone marrow." (PMID 18416830, 2008). "Occasionally other B-cell-derived neoplasms (B-cell lymphomas including large B-cell lymphomas with plasma cell differentiation (for example, plasmablastic lymphoma) and B-lymphoblastic leukemia/lymphoma) will be treated with an anti-CD38 therapy." (PMID 40075660, 2025). "This study examined the potential effects of CD38 expression and increased extracellular ADO production in B-cell lymphoma on various hematological and clinical parameters and their possible connection to the PD-1/PD-L1 axis." (PMID 39805878, 2025). "In this study, we aim to analyze the effects of elevated CD38 expression and extracellular ADO on different hematological and clinical parameters in mature B-cell lymphoma patients and their link to the soluble counterparts of the PD-1/PD-L1 axis." (PMID 39805878, 2025). "This study explored the potential impact of CD38 expression and elevated extracellular ADO on B-cell lymphoma alongside their link with the PD-1/PD-L1 axis." (PMID 39805878, 2025). "For B-cell lymphomas, emphasis is placed on the use of B-cell markers (CD19 and CD20) and other critical antigens (CD5, CD10, and CD38) for classification." (PMID 40075660, 2025).
B-cell lymphoma (continued). "This study examines the impact of heightened CD38 expression and extracellular ADO on various hematological and clinical parameters in patients with mature B-cell lymphoma, alongside their correlation with the soluble counterparts of the PD-1/PD-L1 axis." (PMID 39805878, 2025). "Using the cutoff ≥ 20% for CD38 expression by flow cytometry as an indicator of positivity, mature B-cell lymphoma patients were divided into CD38 positive (No. = 48) and CD38 negative (No. = 42) patients." (PMID 39805878, 2025). "Armed with these compelling data, we meticulously crafted our study to investigate the potential influence of heightened CD38 expression and extracellular ADO production on various demographic, clinical, and hematological parameters in mature B-cell lymphoma patients, including CLL and B-NHL." (PMID 39805878, 2025). "Other small B-cell lymphomas with plasmacytic differentiation (MALToma, follicular lymphoma, monomorphic B-cell lymphoma) were discounted on the absence of a background population of small neoplastic B cells and the uniform CD38+/CD138+/MUM-1+/Igκ-restricted plasma-cell phenotype." (PMID 41200196, 2025). "Our comprehensive study, which thoroughly investigated the link between elevated CD38 expression and extracellular ADO production with the PD-1/PD-L1 axis, uncovered a positive correlation between sPD-L1, sPD-1, sADO, and CD38 expression in all mature B-cell lymphoma patients." (PMID 39805878, 2025). "Bone marrow biopsy and aspirate showed a scant low-grade B-cell lymphoma that coexpressed the B cell markers CD19 and CD20, as well as the CLL markers CD5 and CD23, but lacked CD10 or CD38." (PMID 29740389, 2018). "However, specific immunohistochemical markers for B-cell lymphoma, including CD5, CD10, CD23, BCL6, CyclinD-1, and CD38, which are typically negative." (PMID 39834941, 2024).
hepatocellular carcinoma (19 papers, 2019 to 2025). A malignant tumor that arises from hepatocytes. "Another report showed that the resistance of hepatocellular carcinoma to PD-1/PD-L1 antibodies might be caused by the upregulation of CD38 in tumor cells." (PMID 36605482, 2023). "Indeed, in hepatocellular carcinoma, CD38+ macrophage density associates with improved prognosis and sensitivity to PD-1/PD-L1 immunotherapy." (PMID 34830895, 2021). "In hepatocellular carcinoma (HCC), high density of CD38 + macrophage was associated with improved survival." (PMID 40382743, 2025). "For instance, CD38 has been identified as a co-exhaustion marker in CD8+ tissue-resident memory T cells in hepatocellular carcinoma (HCC), correlating with increased PD-1 expression and higher histopathological grades." (PMID 41488275, 2025). "A recent study demonstrated that hepatocellular carcinoma patients with a high proportion of CD38+ immune cells achieved higher overall response rate of immune-checkpoint blockade therapy." (PMID 34211854, 2021). "High CD38 expression has been observed in hepatic carcinoma TME and in tumor infiltrating lymphocytes (TILs)." (PMID 33727923, 2021). "CD38 also seems to play a role in the tumor microenvironments of solid tumors, with preclinical research revealing that CD38 is overexpressed in various tumor cell lines, such as nasopharyngeal carcinoma, hepatocellular carcinoma, and neuroblastoma cells." (PMID 37840445, 2023). "Moreover, we also observed that OA triggered a marked increase in CD38 expression in mouse hepatoma Hep1-6 cells." (PMID 34803499, 2021). "Recent preclinical trials have revealed a significant breakthrough resistance to anti-PD-1/PD-L1 immunotherapy in various solid tumors, including hepatocellular carcinoma (HCC) and multiple myeloma (MM), is instigated by the up-regulation of CD38 on tumor cells." (PMID 39805878, 2025). "Similar to Innate Pharma’s ANKETTM platform, Cytovia Therapeutics has leveraged its FLEX-NK platform to engineer CYT-303 and CYT-338 NKCEs, targeting the CD38 antigen for hematological malignancies and GPC-3 for hepatocellular carcinoma." (PMID 39911822, 2024).
malaria (18 papers, 2008 to 2024). Malaria is a serious and sometimes fatal disease caused by a parasite that commonly infects a certain type of mosquito which feeds on humans. "A recent report associated CD4+ T cells expressing the degranulation marker CD107a with protection against malaria in sporozoite-immunized volunteers, and CD38 has been implicated in the cytotoxic activity of NK cells." (PMID 27662621, 2016). "CD38, a glycoprotein with extracellular enzyme function, has a potentially cytotoxic function in malaria-infected individuals, as evidenced by the finding that CD38+CD4+ T-cell expansion is significantly correlated with a reduction in blood parasites." (PMID 38515134, 2024). "We assessed CD98 expression during and after malaria in plasmablasts (CD27+CD38+), transitional/naive IgD+ B cells, and IgD- B cell subsets (atypical [CD27-CD21-], memory [CD27+CD21+] and activated memory [CD27+CD21-])." (PMID 37968278, 2023). "In this study, we identified a population of CD4+ T cells that expresses very high levels of CD4 and CD38 (CD4hiCD38hi) in adult malaria patients living in malaria‐endemic regions." (PMID 33282291, 2020). "CD38+/HLA-DR+ expression on T cells has been proposed as a marker of activation in malaria immune responses." (PMID 28369062, 2017). "In contrast, elevation of the memory 3 (CD38+IgD-) B cell subset was observed in the acute clinical malaria compared to the same population following recovery (P = 0.00) and to age-matched healthy controls (P = 0.01)." (PMID 19019204, 2008). "Children with acute clinical malaria had significantly lower naive 1 (CD38-IgD+) B cell subsets compared to the same population following recovery (P = 0.03) and to age-matched healthy controls (P = 0.00)." (PMID 19019204, 2008). "Characterization of the CD19+ B cell subsets in the peripheral blood based on expression of IgD and CD38 revealed a significant decrease in the numbers of naive 1 CD38-IgD+ B cells while there was an increase in CD38+IgD- memory 3 B cells during acute malaria." (PMID 19019204, 2008). "This mirrors the increase in the naive 2 (CD38+IgD+) B cell subset during both acute clinical malaria and recovery compared to healthy controls (P = 0.04 and P = 0.01 respectively)." (PMID 19019204, 2008). "CD8+ T cells were the main T cell subset expressing granzyme B. The proportion of granzyme B+ CD8+ T cells was significantly higher in children with complicated malaria than in uncomplicated malaria, whereas the activation marker CD38 on CD8+ T cells showed similar expression levels." (PMID 31921176, 2019). "While mouse #770 was naïve and lacked CD38+ plasmablasts, mouse #771 was sampled 9 days after injection with sheep red blood cells and mouse #755 was sampled 10 days after two immunizations of a malaria protein, thus both showed CD38+ cells, indicative of plasmablasts." (PMID 29632541, 2018). "However, when patients were segregated by malaria episodes, higher proportions of plasma cells and Ki67+ and Ki67+CD38+ plasma cells were found in first-time infected individuals." (PMID 28700710, 2017). "The expansion of this CD38+ CD4+ T population following infection and its significant association with reduced blood-stage parasite burden is consistent with an important functional role for these cells in protective immunity to malaria in humans." (PMID 27662621, 2016). "As an alternative approach to detect malaria vaccine-reactive CD8+ T cells, experiments were carried out to determine whether CD8+ T cells responding to the malaria vaccine also up-regulated the expression of CD38+ and HLA-DRhi early activation markers." (PMID 24168370, 2013). "Interestingly, the memory 4 (CD38-IgD-) B cell subset was significantly lower in both acute clinical malaria and recovery compared to healthy controls (P = 0.01 and P = 0.00 respectively)." (PMID 19019204, 2008).
malaria (continued). "Whether the CD38‐expressing CD4+ T cells associated with treatment failure in clinical malaria in Uganda had increased expression of CD4 was not reported." (PMID 33282291, 2020). "However, the function and characteristics of CD38‐expressing CD4+ T cells in individuals naturally exposed to malaria, and during an acute malarial infection, are unknown." (PMID 33282291, 2020). "However, since red blood cells lack MHC-II molecules, so the mechanism by which CD38+ CD4+ T cells could exert their cytotoxic function in blood-stage malaria remains to be elucidated." (PMID 27662621, 2016). "Thus, in malaria-naive volunteers, reduced parasite burden during primary blood-stage P. falciparum infection was associated with the expansion of a specific subset of CD4+ T cells expressing the activation marker CD38." (PMID 27662621, 2016). "There was a significant positive correlation between plasma neopterin levels and the percentage of HLA-DR + CD38 + CD4+ T cells during the malaria phase (P = 0.002; r = 0.493), suggesting that the activation of CD4+ T cells was associated with higher concentrations of neopterin induced by malaria." (PMID 25487036, 2014). "Consistent with scRNAseq data, at day 0 during malaria, there was significantly higher proportion of Tr1 cells expressing CD120b, CTLA-4, TIM-3, PD1, CD38 and ICOS." (PMID 37968278, 2023). "Flow cytometric analysis of PBMCs from patients with either P. falciparum or P. knowlesi malaria revealed a pronounced population of CD4+ T cells co‐expressing very high levels of CD4 and CD38 we have termed CD4hiCD38hi T cells." (PMID 33282291, 2020). "In most cases of acute falciparum malaria or knowlesi malaria, we observed a distinctive and unexpected population of CD4+ T cells that co‐expressed high levels of CD38 and CD4, which we have termed CD4hiCD38hi cells." (PMID 33282291, 2020). "Additionally, higher proportions of Th1 cells also expressed CTLA-4, TIM-3, CD38 and ICOS during malaria." (PMID 37968278, 2023). "It demonstrated that IL21R was expressed in healthy individuals in malaria-endemic areas before the start of the malaria season and down-regulated a week after treatment of the first acute malaria episode (in convalescence), while TLR7, TLR9, PRDM1, and CD38 showed the opposite pattern." (PMID 36380692, 2022). "Interestingly, the expression of the activation marker CD38 and the immune checkpoint regulator PD-1 was not different between children with uncomplicated or severe malaria in our study." (PMID 31921176, 2019). "Moreover, the CD4+ T cell activation level, as indicated by the percentage of HLA-DR + CD38 + CD4+ T cells, was shown to be positively correlated with the percentage of annexin V + CD4+ TCM and TEM cells during the malaria phase (P = 0.031, r = 0.44 and P = 0.050, r = 0.404; respectively)." (PMID 25487036, 2014).